PLG (plasminogen)
Diseases named in the same sentence as PLG in open-access papers (continued):
Sharing a sentence is not in itself a finding about the gene and the disease.
infection (continued). "For that purpose, an hBMEC line that maintains the morphological and functional properties of primary brain endothelium was used to evaluate the adhesion, invasion and injury of hBMECs after infection of GBS preincubated with or without human plasminogen and tPA." (PMID 23658816, 2013). "Indeed, A/Netherland/602/09 virus replication in the lungs was not affected by plasminogen deficiency, while infected PLG-KO mice were protected from infection." (PMID 23555246, 2013). "However, PLG interacted with NCL, not ANXA2, during EV-A71 infection." (PMID 40377310, 2025).
cardiovascular disease (21 papers, 2011 to 2025). "Lp(a) is a unique lipoprotein with structural similarities to plasminogen, and elevated levels are a significant risk factor for cardiovascular disease." (PMID 39044888, 2024). "A high level of circulating plasminogen can be indicative of risk of cardiovascular disease, but is also a factor in tissue remodelling." (PMID 25133674, 2014). "Many of the identified proteins are known markers, risk factors, or proteins known to be involved in cardiovascular disease; e.g. transthyretin, apoA1, fibrinogen, serum amyloid A protein, haptoglobin, plasminogen, and others." (PMID 21631938, 2011). "Intravenous fibrinolyticagents are essential for the treatmentof cardiovascular diseases, acting through plasminogen activationto dissolve thrombi." (PMID 40454077, 2025). "However, the interaction analysis reveals that such fluxes can significantly amplify the effect size of risk variants mapped to the PLG, BCAR1 and TGFB1 risk loci, respectively, providing insights into their roles in cardiovascular disease." (PMID 40175777, 2025). "Among these were protein biomarkers for different organ diseases such as deficiency of thyroid binding (thyroxine-binding globulin), chronic kidney dysfunctions (cystatin C), hypercoagulation disorders (plasminogen), and cardiovascular diseases (apolipoprotein A1, B)." (PMID 22538116, 2012). "The gene symbols like HABP2, PLG, PNPLA3, and TM6SF2 exhibit specific expression in hepatic tissue, and our study also suggests their potential impact on cardiovascular disease." (PMID 38523778, 2024). "More importantly, both ratios of VWF:Plasminogen and SerpinC1:Plasminogen were associated with reverse LV remodeling in post-AMI patients, independent of other cardiovascular disease risk factors." (PMID 36613770, 2022).
bacterial infection (8 papers, 2014 to 2021). "Binding and activation of the human plasminogen is an established virulence function in several bacterial infections." (PMID 24833341, 2014). "Circumstantial evidence suggests that this bacterial infection may be involved in the induction of components of the plasminogen activation system in the gastric mucosa, in particular uPAR." (PMID 32660136, 2020). "Additionally, we also tested and confirmed the binding capabilities to human plasminogen and fibronectin, which are required for innate immune response against bacterial infection." (PMID 32373096, 2020). "Plasminogen (PLG) and keratin (KRT1) proteins are expressed in epithelial cells and are important in bacterial infection pathways." (PMID 32765254, 2020).
infectious disease (4 papers, 2008 to 2022). A disorder directly resulting from the presence and activity of a microbial, viral, or parasitic agent in humans. "Plasminogen (PLG) was one of the proteins involved in infectious disease pathway and had higher expression in group N." (PMID 36585464, 2022). "The fibrinolytic pathway is increasingly recognized in infectious disease pathogenesis, and this is the first report to link plasminogen with a filamentous fungus." (PMID 18566672, 2008). "Among the infectious disease KEGG class, influenza A was the most differentiated pathways and PLG was one of the most significantly differentially expressed proteins in the pathway." (PMID 36585464, 2022).
genetic disease (2 papers, 2022 to 2024). "Congenital plasminogen deficiency is a rare genetic disorder caused by an alteration in the PLG gene." (PMID 34861103, 2022).
heart disease (2 papers, 2024). "Thus, this study has two objectives, first to measure the concentration of urinary proteases [plasminogen, heavy chain (plasminogen), furin, and prostasin] in infants with heart disease compared to healthy infants." (PMID 38379911, 2024).
inflammation (2 papers, 2013 to 2018). Aberrant reaction of the microcirculation characterized by movement of fluid and leukocytes from the blood into extravascular tissues. "Mechanistically, the mode of action of plasminogen-driven lung inflammation was through fibrinolysis." (PMID 23555246, 2013).
kidney disease (2 papers, 2009 to 2026). "Although it is well-established that the regulation of plasminogen activation plays a crucial role in kidney disease, it is difficult to speculate on the biological relevance of the transcript-specific findings for PLG as only little is known about the functions of the two PLG transcripts." (PMID 19277110, 2009).
myopathy (1 paper, 2022). A disease of the muscle in which the muscle fibers do not function properly. "PAI-1 plays a unique role in response to skeletal muscle injury and myopathy, highlighting the importance of the plasminogen system and the remodeling of the ECM of skeletal muscle." (PMID 36060470, 2022).
respiratory disease (1 paper, 2022). "Interestingly, plasminogen differed only between the two disease groups due to a reduced level in non‐COVID respiratory disease (p < .01), with uPA also attenuated in this disease group." (PMID 35780481, 2022).
urological disease (1 paper, 2022). "C3 and PLG were selected as hub proteins associated with renal and urological disease." (PMID 36211816, 2022).
vasculopathy (1 paper, 2025). "Mice deficient in the urokinase-type plasminogen activator receptor (uPAR), which functions with its ligand urokinase-type plasminogen activator (uPA) in the plasminogen activation system, exhibit impaired fibrinolysis and spontaneously develop vasculopathy and fibrosis, closely mirroring human SSc." (PMID 40819722, 2025).
PLG also shares sentences with these, for which no sentence is quoted: thrombophilia (8 papers); Thrombocytopenia (6); Arterial thrombosis (3); neurological diseases (3); venous thromboembolism (3); adenocarcinoma (2); colorectal adenocarcinoma (2); congestive heart failure (2); cutaneous melanoma (2); dermatitis (2); diabetic retinopathy (2); dysfibrinogenemia (2); dyslipidemia (2); liver cancer (2); meningioma (2); metabolic disorders (2); metastatic disease (2); obstructive hydrocephalus (2); polycystic ovary syndrome (2); prostatitis (2); respiratory failure (2); thyroid cancer (2); acquired angioedema (1); acute lymphoblastic leukemia (1); acute myocardial infarction (1); allergic bronchopulmonary aspergillosis (1); allergic rhinitis (1); ANCA-associated vasculitis (1); antiphospholipid syndrome (1); atrial fibrillation (1).
A further 84 diseases each share a sentence with PLG in 1 paper.